EZH2 (enhancer of zeste 2 polycomb repressive complex 2 subunit)
Diseases named in the same sentence as EZH2 in open-access papers (continued):
Sharing a sentence is not in itself a finding about the gene and the disease.
ovarian carcinoma (continued). "Indeed, LSD1 inhibition was recently combined with HDAC and EZH2 inhibitors in treatment strategies in acute myeloid leukemia and glioblastoma, as well as in breast and ovarian cancer." (PMID 30220105, 2018). "Our previous work showed that EZH2 is up-regulated in epithelial ovarian cancer (EOC) and that high EZH2 expression significantly correlates with poor cell differentiation, advanced FIGO (The International Federation of Gynecology and Obstetrics) stage and positive lymph node metastasis." (PMID 28620234, 2017). "This evidence suggests a significant contribution of TIMP2 to EZH2 function in ovarian cancer." (PMID 28620234, 2017). "EZH2 promoted ovarian cancer invasion and migration, which could be largely reversed by TIMP2 down-regulation in vitro and in vivo." (PMID 28620234, 2017). "Current EZH2-targeting inhibitors have been used clinically to treat ovarian cancer." (PMID 28968986, 2017). "Analysis of EZH2 mRNA expression data from TCGA database and GEO portal revealed that EZH2 was significantly up-regulated in ovarian cancer compared with normal controls and high EZH2 expression was related to advanced FIGO stage, poor differentiation, and metastasis." (PMID 28620234, 2017). "Importantly, the percentage of EZH2+ CD8+ T cells in the ovarian cancer tissues is a stronger predictor of overall and progression-free survival compared to the percentage of CD8+ T cells." (PMID 27793053, 2016). "Therefore, the exact link between let-7e and EZH2 expression in ovarian carcinoma cells remains elusive." (PMID 26992233, 2016). "Interestingly, a recent study showed that ovarian cancer cells were insensitive to EZH2 inhibition in 2D culture, but sensitive to such treatment in 3D culture." (PMID 25671303, 2015). "EZH2 and its interactors were also identified, which may be used as targets to modulate drug resistance and thus benefit the treatment of ovarian cancer." (PMID 25955318, 2015). "Combination treatment of EZH2 inhibitor together with anti-estrogen therapy may be a novel strategy against ovarian cancer." (PMID 25545504, 2014). "Furthermore, higher levels of EZH2 have been seen in a subpopulation of ovarian cancer cells with stem cell-like properties at relapse following platinum-based chemotherapy." (PMID 24971229, 2014). "Furthermore, chemotherapy enhances the cancer stem cell-like population in ovarian cancer patients and cancer cell lines with high EZH2 expression." (PMID 25431950, 2014). "Interestingly, ovarian cancer patients with low EZH2 level show a positive correlation between the expression of E2F6 and c-KIT." (PMID 25545504, 2014). "Inhibition of the EZH2 activity together with anti-estrogen therapy may therefore be effective against ovarian cancer." (PMID 25545504, 2014). "It has been reported consistently that EZH2, which regulates the methylation program, may regulate E-cadherin expression in ovarian carcinoma." (PMID 24677166, 2014). "Importantly, a positive correlation of E2F6 and c-KIT is only observed in ovarian cancer patients with low EZH2 expression." (PMID 25545504, 2014). "Furthermore, down-regulation of EZH2 was shown to resensitize cisplatin resistant ovarian cancer cells to cisplatin and decrease H3K27me3 levels." (PMID 24971229, 2014). "EZH2 has been proposed as an oncogene in many types of cancer including ovarian carcinoma." (PMID 24677166, 2014). "Our data suggest that Dicer is involved in numerous biological/pathological processes, including drug resistance in ovarian cancer, and that its expression may be regulated by EZH2." (PMID 23599754, 2013). "Conversely, knockdown of EZH2 re-sensitized drug-resistant ovarian cancer cells to cisplatin." (PMID 23494175, 2013). "Thus, inhibiting EZH2/PRC2 activity represents an attractive strategy for developing ovarian cancer therapeutics by targeting both ovarian cancer cells and ovarian tumor microenvironment." (PMID 23494175, 2013).
ovarian carcinoma (continued). "To investigate whether EZH2 is involved in the regulation of Dicer expression in ovarian cancer, we analyzed the alteration in Dicer expression following EZH2 depletion mediated by shRNA using qPCR and western blot analysis." (PMID 23599754, 2013). "A recent study showed that targeting EZH2 via siRNA could be used to reduce angiogenesis and ovarian cancer growth proving the feasibility for using EZH2 as an important therapeutic target." (PMID 21814622, 2011). "Also, the frequent overexpression of EZH2 in human epithelial ovarian cancer cells promotes cellular proliferation and invasive ability, further supporting its possibility as a novel therapeutic target." (PMID 21814622, 2011). "In ovarian cancer specifically, histone marks such as the repressive H3K27me3 mark and active H3K4me3 mark are considered markers of bivalent genes, poised to be silenced during drug resistance in ovarian cancers, particularly regulated by the EZH2 protein complex." (PMID 37853473, 2023). "Hence, combinational therapies including EZH2 inhibitors may prove to be a promising milestone in developing therapeutic strategies for ovarian cancer treatment." (PMID 37634008, 2023). "Besides, in HR-proficient ovarian cancer, EZH2 inhibition could promote sensitivity to PARP inhibitors via upregulation of MAD2L2 in a CARM1-dependent manner." (PMID 36793373, 2023). "In addition to studies that focus on the events downstream of EZH2, several studies describe the roles of microRNAs and lncRNAs in a cascade that leads to changed EZH2 expression or activity and a subsequent modulation of cisplatin resistance in ovarian cancer." (PMID 36230683, 2022). "In addition, EZH2 has been shown to be upregulated in the side population of ovarian cancer cells, which are stem cell-like cells that are enriched by chemotherapy, suggesting that overexpression of EZH2 in ovarian CSCs may contribute to chemoresistance." (PMID 33408782, 2021). "Therefore, we considered CDX1 and FOXC1 are targets of EZH2 in ovarian cancer." (PMID 33336896, 2021). "However, the H3K27me3-related molecular mechanism affected by EZH2 in ovarian cancer remains unclear." (PMID 33163485, 2020). "However, it only investigated the expression and function of EZH2 in ovarian cancer, and the underlying mechanism was not discussed." (PMID 33292225, 2020). "To explore whether EZH2 regulates Et-miRNAs through histone H3K27 trimethylation on the Et-miRNA promoter, we carried out the CHIP assay near the transcription start site (TSS) on the Et-miRNA promoter region using the EZH2 and H3K27me3 antibodies in the ovarian cancer cell line A2780." (PMID 33718109, 2020). "Thus, investigating the functions and potential mechanisms of EZH2 may provide important insights into the treatment of ovarian cancer." (PMID 33163485, 2020). "Moreover, there is also no EZH2 mutation data in epithelial ovarian cancer on the advanced The Cancer Genome Atlas (TCGA) database." (PMID 33163485, 2020). "Thus, CARM1 overexpression and/or amplification may serve as a predictive marker for further development of EZH2 inhibitor as a potential therapy in ovarian cancer." (PMID 29434212, 2018). "Similarly, the enhanced migration and invasion of ovarian cancer cells induced by ectopic EZH2 expression could be relieved by co-expression of TIMP2." (PMID 28620234, 2017). "This study may contribute to the application of EZH2 inhibitors in ovarian cancer therapy." (PMID 28620234, 2017). "In addition, miR-101 was found to target EZH2 directly in ovarian cancer cell lines." (PMID 26992233, 2016).
ovarian carcinoma (continued). "Furthermore, an elevated expression of EZH2, a methyltransferase subunit of the PRC2 complex, has been shown to be associated with advanced stages of ovarian cancer and to be independently associated with shorter overall survival in ovarian cancer patients." (PMID 26992233, 2016). "The enzyme Enhancer of Zeste Homolog 2(EZH2), a methyltransferase, is overexpressed in cisplatin-resistant ovarian cancer cells." (PMID 39757310, 2025). "In a CARM1-dependent way, EZH2 inhibitors can increase MAD2L2 and make HR-proficient ovarian cancer more sensitive to PARPi." (PMID 40612876, 2025). "Specially, a study reported that the combination of EZH2 inhibitors and PARP1 inhibitors enhanced lethality in homologous recombination (HR)-proficient and CARM1-high ovarian cancer." (PMID 40661778, 2025). "It has been shown that lncRNA-ATB inhibition decreases the enrichment of EZH2 in the CDX1, LATS2, FOXC1, and E-cadherin promoters and decreases the histone trimethylation of their promoters in ovarian cancer cells (Chen and An, 2021)." (PMID 39967908, 2025). "For example, EZH2-mediated H3K27me3 and DNMT1-mediated DNA methylation in ovarian cancer reduce the levels of the chemokines CXCL9 and CXCL10 secreted by helper T cells (Th1), increasing CD8+ T cell infiltration, and inhibiting tumor growth." (PMID 38988323, 2024). "It was observed that EZH2, a histone 3 lysine 27 (H3K27) methyltransferase, was overexpressed in cisplatin-resistant ovarian cancer cells compared with cisplatin-sensitive cells." (PMID 38256203, 2024). "Here, we identified EZH2 as a cofactor for CHD4 and established the physiological significance of its interaction with CHD4 in the context of ovarian cancer progression." (PMID 36681835, 2023). "A study indicates that EZH2 inhibits chemokines, such as CXCL9 and CXCL10, thus impairing the trafficking for CD8+ T cells in human ovarian carcinoma." (PMID 35911718, 2022). "The lncRNA ATB binds to EZH2 and downregulates the expression of DAB2IP, CDH1, LATS2, FOXC1 and CDX1, thus facilitating the progression of ovarian cancer." (PMID 34890108, 2022). "EZH2 can methylate the promoter of TIMP2, thereby inhibiting TIMP2 expression and promoting metastasis in ovarian cancer." (PMID 35414793, 2022). "We also verified that the transcription levels of the histone methylation-related genes EZH2, KDM8, STED5, and SMYD3 decreased significantly after MLN4924 treatment of ovarian cancer cells." (PMID 35864225, 2022). "Both genetic and pharmacological inhibition of EZH2 in vitro enhanced IFN-γ-mediated induction of Th1-type chemokines, such as CXCL9 and CXCL10, in human ovarian cancer cells." (PMID 34737746, 2021). "In a cisplatin resistance of ovarian cancer cells study, the upregulation of miR-138-5p enhanced the chemosensitivity of DDP-resistant cells and apoptosis by decreasing the expression of EZH2." (PMID 34790699, 2021). "DNA methyltransferase (DNMT) and enhancer of zeste homolog 2 (EZH2) can mediate DNA methylation and histone lysine methylation, respectively, to suppress the expression of CXCL9 and CXCL10 in ovarian cancer." (PMID 33859752, 2021). "EZH2 and DNMT inhibitor treatment increased T cell infiltration in murine models of ovarian cancer and improved the efficacy of immunotherapies." (PMID 33403469, 2021). "In conclusion, our findings establish a previously unrecognized but especially strong connection between EZH2/CHK1 signaling, CSCs and platinum resistance in epithelial ovarian cancer." (PMID 33408782, 2021). "For example, Melk can enhance the bortezomib resistance of natural killer/T-cell lymphama through EZH2, while the infection of CDK1 expression and activity reduced ovarian cancer growth." (PMID 33956061, 2021). "EZH2 is overexpressed in patients with EOC and promotes proliferation, inhibits apoptosis, and enhances angiogenesis in ovarian cancer." (PMID 34900746, 2021).
ovarian carcinoma (continued). "The ovarian, skin, prostate and soft tissue tumors are characterized by over 1% amplification frequency of EZH2 and EED genes with the highest frequency in ovarian cancer: 11.4% and 9.84%, respectively." (PMID 34202528, 2021). "Enhancer of zester homolog 2 (EZH2), a histone methyl transferase that mediates H3K27me3 through polycomb repressive complex 2 (PRC2), is overexpressed in ovarian cancer and promotes malignant proliferation." (PMID 33718109, 2020). "However, EZH2 mutation has not been reported in epithelial ovarian cancer." (PMID 33163485, 2020). "EZH2/PRC2 methylates H3K27 and leads to transcriptional silence of target genes in multiple subtypes of cancers, including ovarian cancer, breast cancer, PC, T-cell ALL and non-Hodgkin lymphoma." (PMID 32340605, 2020). "Then the correlation of the key components of two EZH2 pathways EZH2/H3K27Me3 and pAkt1/pS21EZH2 to chemotherapy response, OS and PFS of ovarian cancer patients were assessed independently and in combination." (PMID 32435534, 2020). "In ovarian carcinoma, LINC00511 was able to suppress P21 expression by interacting with EZH2, subsequently inhibiting tumor cell proliferation." (PMID 32713253, 2020). "Therefore, EZH2 may also be regulated by KDM2B in ovarian cancer." (PMID 33163485, 2020). "Of note, the new potential targets EZH2 and UBE2C were amplified in around 10% and 6% of ovarian cancers, respectively." (PMID 29575713, 2018). "For example, in ovarian cancer, tumor cell production of chemokines CXCL9 and CXCL10 are epigenetically repressed by EZH2-mediated H3K27me3 and DNMT1-mediated DNA methylation." (PMID 30740111, 2018). "Here, the authors show that EZH2 inhibition suppresses growth in CARM1-expressing epithelial ovarian cancer, and examine the mechanism of how CARM1 promotes EZH2-mediated tumor suppressor gene silencing." (PMID 29434212, 2018). "EZH2 suppressed TIMP2 expression and increased MMP activity, which subsequently promoted ovarian cancer cell migration and invasion in vitro and in vivo." (PMID 28620234, 2017). "Enhancer of zeste homolog 2 (EZH2) is a catalytic subunit of polycomb repressive complex 2 (PRC2), which represses genes involved in tumorigenesis (e.g., hMLH1, ARHI and RASSF1A in ovarian cancer) via methylation of lysine 27 of histone 3 (H3K27)." (PMID 26848980, 2016). "An inverse relation between EZH2 and DLC1 expression was observed in the liver, lung, breast, prostate, and ovarian cancer tissues." (PMID 23826380, 2013). "EZH2 and SMARCA4 are likely candidates to beassociated with ovarian cancer since they are amplified and/or overexpressed in anumber of cancers including prostate, gastric, and breast." (PMID 21423607, 2011). "Following further investigation, the team found that EZH2 inhibitors increased the expression of MAD2L2 and rendered HR‐proficient epithelial ovarian cancer (EOC) sensitive to poly (adenosine diphosphate‐ribose) polymerase (PARP) inhibitors, dependent on CARM1." (PMID 39964832, 2025). "Additionally, HOTAIR acts as a sponge for MIR138-5p, preventing its interaction with EZH2 (enhancer of zeste 2 polycomb repressive complex 2 subunit) and SIRT1 (sirtuin 1), thus enhancing the resistance of ovarian cancer cells to cisplatin-based chemotherapy." (PMID 39684286, 2024). "Knockdown of EZH2 decreased the level of H3K27 trimethylation (H3K27me3) and enhanced the sensitivity of cisplatin-resistant ovarian cancer cells and tumor xenografts to cisplatin, suggesting a role of EZH2 for cisplatin resistance probably through H3K27 methylation." (PMID 38256203, 2024). "EZH2 upregulation was shown to be the main feature in CTO cells and ovarian epithelial cancers." (PMID 37634008, 2023).
ovarian carcinoma (continued). "A combination of EZH2 inhibitor, PARP inhibitor, and/or immune checkpoint blockers might be synergistic in ovarian cancers." (PMID 37634008, 2023). "Given the recent approval of the EZH2-targeting agent (tazemetostat) by the FDA as a treatment for follicular lymphoma, enhanced therapies may soon be available for suppressing ovarian cancers." (PMID 37634008, 2023). "Moreover, EZH2 and IDH2 are overexpressed in ovarian cancer stem cells, which favor OXPHOS over glycolysis for energy production." (PMID 37210576, 2023). "Similarly, silencing of lncRNA HOTAIR abolished cisplatin resistance via suppression of miR-138-5p-involved EZH2 and SIRT1 in ovarian cancer cells." (PMID 36105363, 2022). "In one study, inhibition of EZH2 did not affect the viability of ovarian cancer stem cells in culture but showed a synergistic effect on reducing viability when combined with cisplatin." (PMID 36359771, 2022). "In ovarian cancer cell lines with high CARM1 expression, EZH2 levels are upregulated, allowing activation of homologous recombination repair by exerting transcriptional repression on nonhomologous recombination repair-related genes, such as MAD2L2 (mitotic arrest deficient 2 like 2, MAD2L2)." (PMID 36263120, 2022). "EZH2 inhibitors harm homologous recombination repair in ovarian cancer cell lines by downregulating the expression of nonhomologous recombination repair-associated genes and thus inhibiting homologous recombination repair by treating them with EZH2 inhibitors." (PMID 36263120, 2022). "In ovarian cancer cell lines, inhibition of EZH2 using DZNep (inhibitor of SAM dependent enzymes), EPZ6438 and GSK126 (selective inhibitor of EZH2) and DNMT (azacytadine) synergistically increase IFN-γ responsiveness, and CXCL9 and CXCL10 expression, while shrinking tumor size." (PMID 34163486, 2021). "Indeed, ARID1A‐mutant ovarian cancer cell lines OVISE and TOV21G have displayed sensitivity to EZH2 inhibition, and in wild‐type ARID1A cells, its knockdown confers EZH2 sensitivity." (PMID 34213777, 2021). "In fact, with the recent approval of the EZH2 inhibitor Tazemetostat by the FDA for treatment of follicular lymphoma, improved therapy for ovarian cancer may soon be readily available." (PMID 34213777, 2021). "By providing previously unidentified evidence that EZH2 promotes the platinum resistance of ovarian CSCs by directly activating CHK1 signaling, our work paves the way for targeting EZH2 to reverse recurrence and platinum resistance in ovarian cancer." (PMID 33408782, 2021). "For instance, EZH2 was overexpressed to repress the production of T helper 1 (Th1)-type chemokines CXCL9 and CXCL10 via trimethylation at H3K27, thus establishing an immune suppressive TME for ovarian cancer." (PMID 32340605, 2020). "In the present study, we demonstrated that HOTAIR/miR-138-5p axis could regulate the DDP-resistance of ovarian cancer by potential targets EZH2 and SIRT1, which could shed light on new therapeutic targets for ovarian cancer treatment." (PMID 32349783, 2020). "Concordantly, Li and colleagues detected high EZH2 expression in 66% of 134 epithelial ovarian cancer cases and absent immunoreactivity in normal ovarian tissues." (PMID 33050946, 2020). "In the present study, we investigated the prognostic value of canonical pathway EZH2/H3K27me3 and non-canonical pathway pAkt1/pS21EZH2 of EZH2 in ovarian cancer." (PMID 32435534, 2020). "Overall, MET effects of GRHL2 overexpression, EZH2 inhibition, and HDAC inhibition were limited in ovarian cancer cells with a full EMT state, as these cells may have additional mechanisms that would hinder the expression of epithelial genes." (PMID 31372511, 2019). "BMI1 and EZH2, which are members of the PRC1 and PRC2 complexes respectively, and therefore partners in the action of lncRNAs in the control of gene expression, have been shown to be deregulated in ovarian cancer." (PMID 26992233, 2016).